GALNT14 (polypeptide N-acetylgalactosaminyltransferase 14)
Diseases named in the same sentence as GALNT14 in open-access papers (continued):
Sharing a sentence is not in itself a finding about the gene and the disease.
non-small cell lung carcinoma (7 papers, 2010 to 2024). A group of at least three distinct histological types of lung cancer, including non-small cell squamous cell carcinoma, adenocarcinoma, and large cell carcinoma. "Previously, we reported that expression of GalNAc-T14 (or GALNT14) was highly associated with poor recurrence-free survival in a clinicogenomics study with 138 non-small cell lung cancer (NSCLC) patients." (PMID 26544896, 2015). "For instance, GALNT3 was proposed as a marker of non-small cell lung cancer prognosis, whereas GALNT6 and GALNT14 itself were proposed as potential tissue biomarkers, since their high expression in breast and gastric carcinomas." (PMID 26309160, 2015).
colorectal cancer (6 papers, 2015 to 2025). A primary or metastatic malignant neoplasm that affects the colon or rectum. "The GALNT14 TT genotype is associated with unfavorable overall survival in patients with stage III colorectal cancer, receiving curative surgery and adjuvant oxaliplatin-based chemotherapy." (PMID 36077753, 2022). "Moreover, the GALNT14 c.802C > T substitution has been reported as a confirmed somatic mutation in the COSMIC project (release 67) since it was found in a patient with colorectal carcinoma." (PMID 26309160, 2015).
lung cancer (6 papers, 2010 to 2022). A malignant neoplasm involving the lung. "Over the past decade, genetic variants of GALNT14 and its gene product have emerged as novel prognostic or therapeutic predictors for various gastrointestinal, ovarian, breast, and lung cancers." (PMID 36376274, 2022). "GALNT14 protein expression was significantly higher in cell lines sensitive to dulanermin and drozitumab compared to that in resistant non–small cell lung cancer (NSCLC) cell lines." (PMID 36077753, 2022).
cholangiocarcinoma (4 papers, 2019 to 2023). A carcinoma that arises from the intrahepatic biliary tree (intrahepatic cholangiocarcinoma) or from the junction, or adjacent to the junction, of the right and left hepatic ducts (hilar cholangiocarcinoma). "The association between the prognosis of patients with resected cholangiocarcinoma and the GALNT14-rs9679162 SNP genotype was examined." (PMID 32098271, 2020). "The predictive value of the GALNT14-rs9679162 SNP has been studied in various gastrointestinal (GI) cancers, including esophageal squamous cell carcinoma, gastric signet ring cell carcinoma, colorectal adenocarcinoma, pancreatic adenocarcinoma, and cholangiocarcinoma." (PMID 32098271, 2020).
gastric cancer (3 papers, 2014 to 2023). A primary or metastatic malignant neoplasm involving the stomach. "GALNT14 has been found in various human tissues since it was first discovered in the gastric cancer cell line MKN45 in 2003." (PMID 38024474, 2023).
colon cancer (2 papers, 2021 to 2024). "Therefore, the GALNT14-rs62139523 “A/G” genotype emerges as a potential biomarker for predicting outcomes in stage II and III colon cancer patients undergoing curative surgery followed by 5-FU-based adjuvant chemotherapy." (PMID 38928347, 2024).
glioma (2 papers, 2016 to 2023). A benign or malignant brain and spinal cord tumor that arises from glial cells (astrocytes, oligodendrocytes, ependymal cells). "The role of GALNT14 in glioma has not been described, nor has its role as part of the human proteome and, thus, requires more research and validation." (PMID 37892181, 2023).
inflammatory bowel disease (2 papers, 2025). A spectrum of small and large bowel inflammatory diseases of unknown etiology. "However, whether patients with inflammatory bowel disease and/or celiac disease who develop IgAN show specific enrichments of GALNT14 mutations or LOF variants needs further investigation." (PMID 40371648, 2025). "With the induction of intestinal inflammation using DSS (a model of human inflammatory bowel disease [IBD]), mesangial deposition of IgA was observed in younger Galnt14–/– mice." (PMID 40153534, 2025).
lung adenocarcinoma (2 papers, 2023). A carcinoma that arises from the lung and is characterized by the presence of malignant glandular epithelial cells. "Overexpression of GALNT14 due to decreased DNA methylation is also associated with poor prognosis for lung adenocarcinoma patients." (PMID 37671061, 2023). "GALNT14 serves as an emerging marker for predicting therapeutic outcomes in multiple tumors, and it has also been identified to be related to paclitaxel resistance in lung adenocarcinoma." (PMID 38024474, 2023).
osteosarcoma (2 papers, 2022 to 2023). A usually aggressive malignant bone-forming mesenchymal neoplasm, predominantly affecting adolescents and young adults. "Kaplan–Meier survival showed that GALNT14 was linked to poor overall survival and disease-free survival in osteosarcoma." (PMID 38024474, 2023). "GALNT14 was closely associated with metastasis, progression, cuproptosis-related genes, and the chemosensitivity of osteosarcoma." (PMID 38024474, 2023). "In vitro experiments suggested that GALNT14 was associated with chemotherapy resistance in osteosarcoma." (PMID 38024474, 2023). "In addition, GALNT14 was also associated with poor DFS in osteosarcoma (p=0.00416, HR = 2.41, 95% CI (1.32, 4.398))." (PMID 38024474, 2023). "In conclusion, we identified a GALNT family gene, GALNT14, that was highly expressed in osteosarcoma." (PMID 38024474, 2023). "We analyzed differentially expressed genes associated with GALNT14 levels using the osteosarcoma expression profile from the TARGET database, which contains the largest sample size of osteosarcoma." (PMID 38024474, 2023). "First, we measured the expression of GALNT14 in normal human osteoblasts, drug-sensitive osteosarcoma, and drug-resistant osteosarcoma by RT-qPCR." (PMID 38024474, 2023). "Our results support the potential application of GALNT14 as a predictive biomarker for the diagnosis and metastasis of osteosarcoma." (PMID 38024474, 2023). "GALNT14 was significantly elevated in osteosarcoma tissue, osteosarcoma cell lines, and metastatic osteosarcoma." (PMID 38024474, 2023). "The correlation between GALNT14 and cuproptosis-related genes in osteosarcoma was analyzed by R language." (PMID 38024474, 2023). "Expression of cuproptosis-related genes was closely related in osteosarcoma, and GALNT14 expression was significantly positively correlated with FDX1, a key regulator of cuproptosis." (PMID 38024474, 2023). "In this study, we analyzed the expression of GALNT14 in osteosarcoma using expression data found in public databases." (PMID 38024474, 2023). "Here, we aimed to explore the expression and potential mechanism of GALNT14 in osteosarcoma through bioinformatics analysis and in vitro experiments." (PMID 38024474, 2023). "Here, we reveal for the first time the significance of GALNT14 in the chemosensitivity of osteosarcoma." (PMID 38024474, 2023). "In summary, our results suggest a possible novel mechanism of GALNT14 involvement in osteosarcoma cell proliferation and death." (PMID 38024474, 2023). "We investigated GALNT14 expression in osteosarcoma using GEO, the TIMER database, and clinical samples." (PMID 38024474, 2023). "We also observed upregulation of GALNT14 in the osteosarcoma cell line U2OS compared to GALNT14 expression in the human osteoblast cell line HOB (p < 0.001)." (PMID 38024474, 2023). "Transcriptome analysis showed that a high expression of GALNT14 and MUC1 in osteosarcoma was associated with poor prognosis." (PMID 36405691, 2022). "qRT-PCR showed that the expression of GALNT14 in osteosarcoma cell lines was also higher than that in the osteoblast cell line, while the opposite result can be seen in MUC1." (PMID 36405691, 2022). "Our study revealed for the first time the expression of GALNT14 in osteosarcoma." (PMID 38024474, 2023). "A siRNA was used to inhibit the expression of GALNT14 in the osteosarcoma cell lines MG-6 and U-2." (PMID 38024474, 2023). "We identified a GALNT family gene, GALNT14, that was highly expressed in osteosarcoma." (PMID 38024474, 2023). "We first performed a detailed analysis of the impact of GALNT14 on OS in osteosarcoma." (PMID 38024474, 2023). "Additionally, we inhibited GALNT14 function in an osteosarcoma cell line by transfecting siRNA and subsequently explored the effect on drug sensitivity by CCK-8, clonogenic assay, and flow cytometry." (PMID 38024474, 2023). "Consistently, increased expression of GALNT14 was identified in osteosarcoma." (PMID 38024474, 2023).
osteosarcoma (continued). "It was observed that GALNT14 was significantly highly expressed in osteosarcoma." (PMID 36405691, 2022). "Finally, the poor prognostic significance of GALNT14 in osteosarcoma was also elucidated." (PMID 38024474, 2023). "Finally, we assessed the significance of GALNT14 in chemosensitivity and prognosis in osteosarcoma." (PMID 38024474, 2023). "However, the function of GALNT14 in osteosarcoma is still unclear." (PMID 38024474, 2023). "We analyzed the correlation of the expression of GALNT14 and 10 cuproptosis-related genes by using the TARGET osteosarcoma dataset." (PMID 38024474, 2023). "Our research revealed a strong correlation between high GALNT14 expression and poor OS and DFS in osteosarcoma." (PMID 38024474, 2023). "However, the prognostic significance of GALNT14 in osteosarcoma remains unknown." (PMID 38024474, 2023). "GALNT14 expression was also elevated in metastatic osteosarcoma compared to the nonmetastatic stage." (PMID 38024474, 2023). "Furthermore, osteosarcoma at the metastatic stage showed an increased GALNT14 level compared to that at the nonmetastatic stage (p=0.004)." (PMID 38024474, 2023).
breast tumours (1 paper, 2016). "Supporting our experimental data, clinical data analysis revealed that the elevated level of GALNT14 in primary breast tumours specifically predicts lung relapse, suggesting the potential use of GALNT14 expression in identifying patients with high risks of pulmonary metastases." (PMID 27982029, 2016).
chronic kidney disease (1 paper, 2025). Impairment of the renal function secondary to chronic kidney damage persisting for three or more months. "We also searched for predicted LOF variants in GALNT14 in 418 individuals with sporadic IgAN among 2,179 patients with chronic kidney disease (CKD) in a study evaluating the diagnostic utility of exome sequencing in CKD." (PMID 40153534, 2025).
colitis (1 paper, 2025). Inflammation of the colon. "Galnt14–/– mice have increased mesangial IgA deposition with aging, and with the induction of chemical colitis, in young mice." (PMID 40153534, 2025). "Alcian blue staining revealed that 8-week-old Galnt14–/– mice also have a reduced mucin layer in the colon, without evidence of inflammation or spontaneous colitis when compared with WT mice." (PMID 40153534, 2025).
COVID-19 (1 paper, 2021). A disease caused by infection with severe acute respiratory syndrome coronavirus 2. "Seven of our significant genes higher (GALNT14, OAS1, CCRL2, OAS3, CCR1, OAS2, SIPA1L2) in COVID-19 and two lower (HLA-DPB1, HLA-DQA2) were identified to overlap." (PMID 34335605, 2021).
embryonal rhabdomyosarcoma of the prostate (1 paper, 2023). "This knowledge might also explain the presence of GALNT14 in tumor cells of embryonal rhabdomyosarcoma of the prostate as this myogenic neoplasm originates from muscle cells." (PMID 37671061, 2023).
head and neck cancer (1 paper, 2022). A primary or metastatic malignant neoplasm affecting the head and neck. "This study showed that GALNT14-rs9679162 genotype and GALNT14 mRNA expression are associated with post-treatment survival in head and neck cancer, and can be used as indicators to predict the response to neoadjuvant chemotherapy." (PMID 36077753, 2022). "The results of this study showed that GALNT14-rs9679162 and mRNA expression were associated with post-treatment survival in head and neck cancer." (PMID 36077753, 2022). "In Xena Functional Genomics Explorer (TCGA) at GDC TCGA and TCGA Head and Neck Cancer profiles, GALNT14 expression was induced by alcohol consumption and upregulated in the late stage of tumors." (PMID 36077753, 2022). "In the Gene Expression Omnibus database (GEO), in the GDS1667/219271_at profile, GALNT14 mRNA expression was higher in HPV-positive than in HPV-negative head and neck cancer cases." (PMID 36077753, 2022). "Therefore, this study analyzed the frequency of the GALNT14-rs9679162 genotype and the expression level of GALNT14 in patients with head and neck cancer." (PMID 36077753, 2022). "However, the relation of GALNT14 and head and neck cancer were nuclear." (PMID 36077753, 2022). "Analysis of the data from the GPL570 platform (HG-U133 plus 2) showed that the expression of GALNT14 mRNA was also not different in pharyngeal cancer tissues, but was lower in head and neck cancer and oral cancer tissues compared to that in the unpaired normal tissues." (PMID 36077753, 2022). "However, the GALNT14-rs9679162 genotype and its expression in head and neck cancers have not been studied." (PMID 36077753, 2022).
keratoconus (1 paper, 2023). A degenerative, structural disorder of the eye, characterized by a cone-shaped protrusion of the cornea. "In particular, one article points to a frameshift variant in homozygosity in the GALNT14 gene as a cause of non-syndromic keratoconus." (PMID 37895187, 2023).
liver cirrhosis (1 paper, 2020). "For example, HCC is tightly linked to liver cirrhosis and male gender, and thus it will be interested to know whether GALNT14 is involved in modulating fibroblast or sex hormone behavior." (PMID 32098271, 2020).
lymph node metastasis (1 paper, 2024). "In the univariate analysis, patients with GALNT14-rs62139523 “A/G” genotype (p = 0.001), lower T stage (pT1 to pT3) (p = 0.010), lymph node metastasis (p = 0.011), and lower circulating CEA levels (p < 0.001) were associated with favorable OS." (PMID 38928347, 2024). "In the subsequent multivariate analysis, all four factors emerged as independent predictors of OS: GALNT14-rs62139523 “A/G” genotype (p = 0.008), lower T stage (pT1 to pT3) (p = 0.022), lymph node metastasis (p = 0.002), and lower circulating CEA levels (p < 0.001)." (PMID 38928347, 2024).
oral cancer (1 paper, 2022). "Seven oral cancer cell lines were used to analyze GALNT14 expression levels in the three GALNT14-rs9679162 genotypes." (PMID 36077753, 2022).
pharynx cancer (1 paper, 2022). A primary or metastatic malignant neoplasm that affects the pharynx. "Analysis of the data from the GPL96 platform (HG-U133) from the Gene Expression Database of Normal and Tumor Tissues (GENT2) revealed that the expression of GALNT14 mRNA was not different in laryngeal and pharynx cancer tissues compared to that in unpaired normal tissues." (PMID 36077753, 2022).
primary immunodeficiency (1 paper, 2023). "High expression of GALNT14 in BPD may induce BPD by activating primary immunodeficiency." (PMID 37478211, 2023).
prostate adenocarcinoma (1 paper, 2023). "However, kidney chromophobe, liver hepatocellular carcinoma, and prostate adenocarcinoma had lower GALNT14 expression than adjacent normal tissues." (PMID 38024474, 2023).
prostate carcinoma (1 paper, 2023). A carcinoma that arises from epithelial cells of the prostate gland. "In addition, this knowledge may help to understand the function of GALNT14 and to elucidate GALNT14-initiated signaling pathways involved in prostate cancer as an increased GALNT14 expression is clearly associated with adverse effects across tumor entities." (PMID 37671061, 2023). "Overall, this work provides a basis for further studies related to paracrine stromal-epithelial interaction in prostate carcinoma and highlights the importance of GALNT14." (PMID 37671061, 2023). "This study provides new insights in the expression of GALNT14 in prostate carcinoma cells." (PMID 37671061, 2023). "Moreover, for prostate carcinoma an induced expression of the N-acetylgalactosaminyltransferase GALNT14 is shown in rare cases of pathology which could help to further characterize this heterogenous tumor." (PMID 37671061, 2023). "Moreover, in prostate carcinoma, GALNT14 expression heavily varied independent of the Gleason score." (PMID 37671061, 2023).
Sepsis (1 paper, 2025). Sepsis is defined as life-threatening organ dysfunction caused by a dysregulated host response to infection. "Validation with an independent dataset confirmed the differential expression patterns of B3GNT5, C1GALT1C1, and GALNT14, reinforcing their potential as robust diagnostic biomarkers for sepsis." (PMID 39981259, 2025). "The expression trends of six Golgi-related genes (B3GNT5, FUT11, ST3GAL5, MAN1C1, C1GALT1C1, and GALNT14) aligned with the patterns observed in the hub genes from the initial sepsis dataset analysis." (PMID 39981259, 2025). "The key genes distinguishing sepsis from healthy conditions include B3GNT5, FUT11, ST3GAL5, MAN1C1, C1GALT1C1, and GALNT14." (PMID 39981259, 2025).